RFC1 (replication factor C subunit 1)
Diseases named in the same sentence as RFC1 in open-access papers (continued):
Sharing a sentence is not in itself a finding about the gene and the disease.
RFC1 also shares sentences with these, for which no sentence is quoted: Ataxia (35 papers); autonomic dysfunction (3); Huntington disease (3); Parkinsonism (3); peripheral neuropathy (3); axonal sensory neuropathy (2); cerebellar-type multiple system atrophy (2); Dystonia (2); episodic ataxia type 2 (2); fragile X syndrome (2); frontotemporal dementia (2); myotonic dystrophy type 2 (2); spinocerebellar ataxia type 8 (2); Adult onset (1); alcoholism (1); Alzheimer disease (1); ataxia telangiectasia (1); Atrophy (1); autism spectrum disorder (1); autosomal recessive cerebellar ataxia (1); autosomal recessive disease (1); benign adult familial myoclonic epilepsy (1); Bradykinesia (1); Cerebellar Ataxia, Neuropathy, Vestibular Areflexia Syndrome (1); Cerebellar atrophy (1); cerebral infarction (1); cerebrotendinous xanthomatosis (1); Chorea (1); coeliac disease (1); conotruncal heart defects (1).
A further 34 diseases each share a sentence with RFC1 in 1 paper.